RARA (retinoic acid receptor alpha)
Diseases named in the same sentence as RARA in open-access papers (continued):
Sharing a sentence is not in itself a finding about the gene and the disease.
tumor (142 papers, 2004 to 2026). "The increased anti‐tumor T cell activity in RARα deficiency would offer a novel opportunity to boost adoptive T cell therapies." (PMID 40068101, 2025). "In contrast, RARα‐deficient CTLs are hyper‐active in making tumor‐populating Teff cells, suggesting that RARα represses Teff differentiation." (PMID 40068101, 2025). "In PDAC cases, increased expression of RARα is reportedly associated with a better prognosis, suggesting that RARα is a tumor suppressor." (PMID 37198667, 2023). "Previously we have reported that loss of RARα and RARβ expression in tumor tissue from advanced NSCLC patients was associated with a worse prognosis." (PMID 33324556, 2020). "In contrast to the protective effects of RARβ, studies have linked increased expression of RARα with formation of tumors of the breast and cervix, potentially by way of an estrogen-mediated pathway." (PMID 26462767, 2015). "We identify RARα as the main retinoid receptor variant mediating the anti-tumor activity of the retinoid." (PMID 25888236, 2015). "More intriguingly, the level of GRP75/RARα/RXRα tripartite complexes was tightly associated with the RA-induced suppression of tumor growth in animals and the histological grade of differentiation in human NB tumors." (PMID 22022577, 2011). "Thus, RARα‐deficient CAR‐T cells demonstrated enhanced tumor infiltration, cytotoxicity, and TME‐modifying properties." (PMID 40068101, 2025). "Thus, RARα deficiency in T cells suppressed tumor growth, whereas over‐expressed RARα increased the growth." (PMID 40068101, 2025). "In order to investigate the molecular mechanisms underlying the RARα aberrant expression in GC, we hypothesized that the infiltration of inflammatory factors, an important feature of the tumor microenvironment, lead to the overexpression of RARα." (PMID 28035062, 2017). "Thus, activation of the RARα pathway is linked to tumor growth inhibition, differentiation and cell death." (PMID 22920668, 2012). "RARa expression has been demonstrated to be positively linked to proliferative activity and to ER expression, whereas RARb may act as a tumour repressor gene, since its expression is progressively lost with increasing proliferative activity of the tumour." (PMID 22276018, 2009). "This approach also allowed us to assess the effect of RARα expression on tumor cells in an antigen‐specific manner." (PMID 40068101, 2025). "RARα‐KO CAR‐T cells were more effective in delaying tumor growth compared to WT or RARα‐TG CAR‐T cells." (PMID 40068101, 2025). "To systematically analyze cellular communication networks in TME, we applied the CellChat analysis to our scRNA seq data obtained for MC38 tumor‐infiltrating T cells in WT, RARα‐KO, and RARα‐TG mice." (PMID 40068101, 2025). "Overall, the RARα level in T cells apparently controls tumor T cell composition, with high and low levels of RARα, respectively, causing a defect and a boost in Teff enrichment in tumors." (PMID 40068101, 2025). "Our results establish RARα as a potent negative regulator of Teff differentiation in tumors and a functionally important target to invigorate anti‐tumor CTL activity." (PMID 40068101, 2025). "In contrast, the CTL frequency in the tumor‐draining lymph nodes (dLN) of RARα‐KO mice was notably decreased compared to that of WT and TG mice." (PMID 40068101, 2025). "In contrast, MC38 tumor growth was greatly accelerated in RARα‐TG mice, often developing ulcers on tumors." (PMID 40068101, 2025). "RAR exists in three isoforms—RARα, RARβ, and RARγ—each with distinct tissue distributions and roles: RARα is expressed in various tissues, RARβ plays a key role in neurogenesis and tumor suppression, and RARγ is vital for skin and bone development." (PMID 40926269, 2025). "The negative regulation of the nuclear HAT activity by RARα also provides an effective mechanism for the decreased trafficking receptor switch and tumor infiltration in RARα‐TG mice." (PMID 40068101, 2025).
tumor (continued). "The host non‐CAR tumor‐infiltrating CTLs in the mice treated with RARα‐KO CAR‐T cells had elevated expression of IFN‐γ, GzmB, and Perforin." (PMID 40068101, 2025). "Taken together, these findings suggest that RARα negatively affects the proliferation of CTLs in the tumor microenvironment." (PMID 40068101, 2025). "The up‐regulated genes in tumor‐infiltrating myeloid cells in RARα‐KO mice included Rnf128, Cd36, Nos2, Prdx1, Cd274, and H2‐Q4, associated with the immune‐activating phenotype." (PMID 40068101, 2025). "Next, we determined the anti‐tumor efficacy of WT, RARα‐KO, and RARα‐TG CAR‐T cells in vivo on existing tumors." (PMID 40068101, 2025). "Among the DEGs, genes expressed at higher levels in RARα‐KO CTLs included major effector molecules required for anti‐tumor immunity, such as Ifng, Gzmb, and Prf1." (PMID 40068101, 2025). "The role of RARα expression in regulating anti‐tumor effector CTL (Teff) differentiation is reported." (PMID 40068101, 2025). "While less pronounced in the Rag1‐KO background, a similar trend of decreased and increased tumor growth was observed in the mice transferred with RARα‐KO T cells and RARα‐TG T cells." (PMID 40068101, 2025). "We investigated the roles of increased or decreased expression of RARα on anti‐tumor CTLs by utilizing animal models with altered expression of RARα." (PMID 40068101, 2025). "While the effects of RARα on the CTL phenotype in both tumor models were similar and consistent, the overall effect on tumor growth was more pronounced in MC38, compared to B16, tumors." (PMID 40068101, 2025). "RARα gene expression is upregulated in CTLs in tumor microenvironments (TME), but its protein expression is downregulated by retinoic acid." (PMID 40068101, 2025). "Generation of chimeric antigen receptor (CAR) T cells with reduced RARα expression produces highly effective CAR T cells with enhanced anti‐tumor cytotoxicity." (PMID 40068101, 2025). "Next, we sought to evaluate the capacity of CIM7 to inhibit CMA and reduce NSCLC tumor growth in vivo as well as the translational potential to inhibit CMA via NCoR1/RARα targeting in NSCLC." (PMID 40490560, 2025). "To determine the impact of the varied expression of RARα in T cells on tumor growth, we subcutaneously implanted MC38 tumor cells into control, RARα‐KO, and RARα‐TG mice." (PMID 40068101, 2025). "The tumors in the three different mouse groups (i.e., WT, RARα‐KO, and RARα‐TG) had distinctive compositions of tumor‐infiltrating T cell clusters." (PMID 40068101, 2025). "We found a positive correlation between the genes upregulated in RARα‐KO tumor‐infiltrating CTLs and the genes upregulated in vitro in RARα‐KO versus WT CTLs." (PMID 40068101, 2025). "In this regard, we demonstrated that the CCR7→ CXCR3 switch was significantly decreased in RARα‐TG CTLs in tumor‐draining lymph nodes." (PMID 40068101, 2025). "Pathognomonic of APL, PML::RARα fusion protein rewires metabolic pathways to feed anabolic tumor cell’s growth." (PMID 40931045, 2025). "Following this type of analysis, 5%, 53% and 42% of the tumor samples showed high, intermediate and low expression levels of RARα, respectively." (PMID 39323992, 2024). "Out of the three distinct RAR genes (RARα, RARβ, and RARγ) that have been identified, RARα interacts with target genes to contribute to tumor growth, metastasis, drug resistance, and other processes." (PMID 38910889, 2024). "RAR activated by retinoic acid, exerts antiproliferative effects in tumor cells and translocation or fusion involving promyelocytic leukemia with RARα leads to acute promyelocytic leukemia (APL) in hematopoietic myeloid cells." (PMID 39327610, 2024). "This decrease in Treg numbers and activity is consistent with studies that have demonstrated an increased efficacy of DC tumor vaccines by blocking RARα signaling and reducing Treg development." (PMID 37341756, 2023).
tumor (continued). "This discovery led to the PML protein being recognised as a tumour suppressor, specifically in acute promyelocytic leukaemia, due to the close association of the PML gene with the retinoic acid receptor-alpha (RAR-α) gene in this disease type." (PMID 38140552, 2023). "One such study determined the expression of RARs in normal and malignant tissues from 76 patients with NSCLC and showed that tumor cells have overexpressed RXRα and RARα and reduced RXRβ, RARβ, and RARγ." (PMID 35631448, 2022). "Collectively, our findings show that concurrent stimulation of GR, ERα, and RARα strongly potentiates neuronal differentiation, triggers metabolic reprogramming, and reduces tumor burden." (PMID 35850708, 2022). "FTO negatively regulates the expression of Ankyrin Repeat and SOCS Box Containing 2 (ASB2) and Retinoic Acid Receptor Alpha (RARA), a cluster tumor suppressor target gene, by post-transcriptionally modulating its m6A abundance and then affecting its stability." (PMID 35422475, 2022). "Specifically, miR-27a was shown to promote tumor cell proliferation in RMS which was attributed to its role in targeting the retinoic acid receptors: retinoic acid alpha receptor (RARA) and retinoic X receptor alpha (RXRA)." (PMID 36033507, 2022). "The mRNA expression of genes of RXRγ, RARα, and RXRα was shown to be considerably lower in tumor specimens, revealing that deregulation of these genes follows the aberrant transformation of lung tissue cells." (PMID 35631448, 2022). "RARα is differentially expressed in different tumor tissues, and it also interacts with its target genes to participate in tumor growth, metastasis, drug resistance and other processes." (PMID 34858481, 2021). "By binding to RARE regions of target genes, RARα can regulate miR-10a and miR-21 transcription to participate in proliferation and motility of tumor cells." (PMID 33902658, 2021). "The oncogenic activity of RARA and tumor suppressor activity of APC observed in our study supported their roles that were reported in previous research." (PMID 35111672, 2021). "The PML gene gained its name as it was discovered as a tumour suppressor that is disrupted in acute promyelocytic leukaemia resulting in its fusion to the gene retinoic acid receptor alpha (RARA)." (PMID 33988819, 2021). "For example, in the proto-oncogene RARA, the activity of prmtr.27493 was remarkably higher in the tumor, while the activity of prmtr.27494 remained unchanged in both tumor and normal samples." (PMID 35111672, 2021). "The anti-tumor activity of hypo-phosphorylated RARα was investigated in TNBC cell models and a xenograft mouse model." (PMID 33902658, 2021). "The findings showed that RARα, RARβ, RARγ, and RXRγ were present in significantly lower levels in the tumor tissues." (PMID 32012980, 2020). "The authors found that the mRNA levels of the nuclear receptor genes RXRγ, RARα, RXRα were significantly decreased in 80%, 65%, and 57% of tumor specimens, respectively, even at early stages." (PMID 32012980, 2020). "Our data depict a new mechanism determined by the presence of PML/RARa in APL tumor cells involving NRF2." (PMID 31905996, 2019). "Here, the expression of RARα was frequently elevated in human GC tissues and cell lines, and its overexpression was closely correlated with tumor size, lymph node metastasis and clinical stages in GC patients." (PMID 28035062, 2017). "Q-PCR and Western blot were performed to detect the expression of RARα in tumor (T) and paired paracarcinoma (P) tissues of 21 GC patients." (PMID 28035062, 2017). "GSK-3 is serine threonine kinase that phosphorylates a wide range of cellular proteins and has both oncogenic and tumor suppressor activities; in particular it inhibits RARα transcriptional activity." (PMID 27331409, 2016). "Although Am80 is selective for RARα and RARβ, which function as the master regulators of granulocytic differentiation and tumor suppression, respectively, it preferentially activates RARα." (PMID 27737899, 2016).
tumor (continued). "We show here that by using the combination of SID decoys and RARα agonist it is possible to help “cure” mice of a TNBC-like tumor." (PMID 27286261, 2016). "Overall, these data demonstrate that PML/RARA impairs PTEN tumor suppressive functions by promoting the transcriptional repression of the PTEN gene and also increasing its degradation." (PMID 27626703, 2016). "RARα is also primarily located in the nucleus of tumor cells, and partly in the cytoplasm, which is consistent with the previous report." (PMID 27689360, 2016). "This showed that the top 8 NR, namely ERα, PGR, DAX1, TLX, PNR, RARγ, RARα and Rev-erbAβ provide the lowest error rate, highlighting these NRs as the most important variables for differentiating the two tumour clusters." (PMID 26280373, 2015). "There were also two processes associated to bone “myelopoiesis of bone marrow” (associated genes NPM1, RARA) and “quantity of trabecular bone” (associated genes CREBBP, SMO)—these findings were present only in the tumour tissue." (PMID 25496518, 2014). "The tumor suppressor promyelocytic leukemia (PML) was first identified as a fusion partner of human retinoic acid receptor alpha (RARα) as the result of a chromosomal translocation discovered in acute PML (APL)." (PMID 23504288, 2013). "Adapalene, Tazarotene, Tamibarotene are retinoids which involved RARA gene with multiple functions including eye vision, immune function, and activation of tumor suppressor genes." (PMID 24564241, 2013). "In contrast, a shift towards RARα activation by the selective RARα agonist Am580 induces a tumor-inhibiting response in MMTV-Myc mice." (PMID 22920668, 2012). "The consequence of this change is down-regulation of tumor suppressive genes such as RARα, RARβ and CRBP1, and possibly others." (PMID 22920668, 2012). "The PML/RARα oncogenic fusion protein is directly responsible for the silencing of the tumor suppressors let-7c and miR-342." (PMID 24278756, 2012). "This reduction in cellular proliferation by the addition of Am580 implies that RARα is the tumor suppressor isotype." (PMID 22920668, 2012). "In a xenograft mouse model of NB and a cohort of patient samples, the formation of tripartite GRP75/RARα/RXRα complexes was inversely correlated with tumor progression and consistently predicted a favorable outcome." (PMID 22022577, 2011). "The correlation between the level of GRP75/RARα/RXRα tripartite complexes and tumor growth was further analyzed in the harvested NB xenografts." (PMID 22022577, 2011). "In spite of all these inhibitory effects of activated RARα we found a significant increase in tumor-free survival when mice null for RARα1 were crossed with MMTV-wnt1 transgenic mice." (PMID 20923554, 2010). "Additionally, the RARα expressed in T cells had a significant impact on the tumor myeloid compartment." (PMID 40068101, 2025). "We implanted the same tumor cells into naïve versus previously tumor‐rejected RARα‐KO mice." (PMID 40068101, 2025). "While RARα agonists and antagonists have been studied for decades for their effects on cancer, the expression and role of RARα itself in regulating cancer, particularly affecting anti‐tumor T cell responses, have been unclear." (PMID 40068101, 2025). "NR1B1/RARα expression is dynamically regulated in cytotoxic lymphocytes (CTLs) in tumors, but the importance of its expression in anti‐tumor CTLs remains unknown." (PMID 40068101, 2025). "Next, we examined tumor infiltration by T cells in WT, RARα‐KO, and RARα‐TG mice." (PMID 40068101, 2025). "In contrast, decreased RARα expression promoted anti‐tumor Teff cells in tumors." (PMID 40068101, 2025). "The RARA signaling pathway plays a crucial role in growth and remodeling in tissue homeostasis and participates in the regulation of multiple crucial biological pathways, such as growth, differentiation, reproduction, and tumor progression." (PMID 38902322, 2024). "In our tumor samples, we determined large amounts of the RARα, RARβ, RXRα and RXRβ transcripts." (PMID 39323992, 2024).
tumor (continued). "Furthermore, in both monotherapy and combination groups, RARA knockdown resulted in reduced tumor volume and weight, an effect that was reversed by overexpression of TXN and PPM1F, which was consistent with vitro experiments." (PMID 38902322, 2024). "WYC-209 exerts anti-tumor effects in GC by down-regulating the expression of WNT4 via RARα." (PMID 38178596, 2024). "The low intracellular level of ATRA in prostate cancer tumours is important because the RAR isoforms have a differential sensitivity towards ATRA transactivation: RARγ is activated at a much lower concentration of ATRA than RARα." (PMID 36768694, 2023). "However, when combined with ATRA, it activated the RARα-Nrf2 complex and blocked Nrf2 activation, leading to ROS accumulation and ROS-dependent anti-tumour effects." (PMID 36482192, 2023). "AM580 is an RARα agonist that has previously shown to reduce tumor size and inhibit proliferation." (PMID 35269414, 2022). "In contrast to RARA, hypermethylation of a promoter (prmtr.29535) inhibits the transcription and may contribute to the intensification of tumor progression." (PMID 35111672, 2021). "RARA triggers anti-proliferative effects in tumor cells by directly regulating gene expression." (PMID 31896739, 2020). "Moreover, as RARβ, also RARα was defined as tumor suppressor silenced by extensive cytosine methylation in the promoter responsible of RARα under-expression in MCF-7 cell line, and probably in the dysregulation of ATRA signaling." (PMID 32012980, 2020). "Tumor-associated GSK-3β is correlated with reduced expression of retinoic acid receptor-β (RARβ), which is caused by GSK-3β-mediated phosphorylation and heterodimerization abrogation of retinoid X receptor (RXRα) with RARα on RARβ promoter." (PMID 31938062, 2020). "The tumorigenic potential of RARα was also evaluated by xenograft tumor in nude mice." (PMID 28035062, 2017). "At each RA concentration, the cancer cell growth outcome seems to reflect the combined effects of both the ‘absence’ of epigenetic transcriptional activation of RARA-targets (e.g. tumor suppressor functions like RARB2 and TGFBR2) and activation of PI3K kinase effectors (e.g. P-AKT)." (PMID 27894085, 2016). "However, in transgenic mice models, TRIM24 is demonstrated as a tumor suppressor and can suppress liver carcinogenesis via interacting with RARα." (PMID 27689360, 2016). "Targeting of HER2 with Lapatinib and RARα with ATRA results in a number of anti-tumor responses." (PMID 25961594, 2015). "We also evaluated whether specific activation of RARα by Am580 had anti-tumor effects in c-Myc-induced tumorigenesis." (PMID 22920668, 2012). "COX-2 expression was not correlated with tumor stages and localisations (data not shown), but was associated with RARα and RARβ mRNA expression in tumor tissue." (PMID 17767717, 2007). "Therefore, ATRA/arsenic combination programme exerts an anti‐tumour effect by induced PML/RARA degradation in cells, from which anti‐tumour efficacy could be dissociated from the trancriptomic effect." (PMID 35001521, 2022). "Besides RARα, other gene products are likely to play a role in the anti-tumor action of ATRA." (PMID 25888236, 2015). "In HCC, all-trans retinoic acid (ATRA) enhances TFPI2 via retinoic acid receptor alpha (RARα), modulated by MAF bZIP transcription factor B (MAFB, activator) and MAFF (repressor), influencing tumor invasion." (PMID 40361374, 2025). "To test this idea, we transduced WT, RARα‐KO, and RARα‐TG CTLs with a retroviral vector expressing a CAR against hCD19 and co‐cultured the cells with hCD19‐expressing B16 or MC38 tumor cells at various effector‐to‐target ratios." (PMID 40068101, 2025). "In contrast, RARα‐TG CAR‐T cells were less efficient than WT CAR‐T cells in killing both B16 and MC38 tumor cells expressing hCD19 antigen in vitro." (PMID 40068101, 2025).